KRAS (KRas proto-oncogene, GTPase)
Diseases named in the same sentence as KRAS in open-access papers (continued):
Sharing a sentence is not in itself a finding about the gene and the disease.
tumor (continued). "Although the presence of KRAS mutation in ctDNA was relatively consistent with that in tumor tissue of the same person, whether the mutant allele fraction (MAF) of KRAS in ctDNA and tumor tissue differed was still not reported." (PMID 31850201, 2019). "We could successfully translate our results into a clinical setting as high levels of Cdk5 were associated with a higher risk of relapse in early-stage MSS CRC patients that did not receive any treatment after primary tumor resection, especially in patients with KRAS-mutant tumors." (PMID 31614664, 2019). "Therefore, Wnt inhibition may prevent tumours developing from more serrated routes, which are often associated with a lack of APC mutation and carry BRAF or KRAS mutations." (PMID 29556067, 2018). "Since our data showed that loss of PTPRS increased the phosphorylation of ERK in tumor cells driven by both mutant KRAS as well as wild-type KRAS, we sought to further confirm the effects of PTPRS knockout (KO) on CRC cells, independent of KRAS mutation status." (PMID 29915291, 2018). "Importantly, depletion of GSK3α/β inhibited MiaPaCa2 but not A549 tumor growth, further supporting the hypothesis that mutant KRas-dependent but not -independent tumors require GSK3α/β for growth and survival." (PMID 30514931, 2018). "One of these cell lines had a KRAS mutation only without a PI3K pathway mutation (HEC50), and the antagonism of the combinations may possibly be partly as a result of the particularly marked anti-tumour efficacy of MEK inhibition alone in this cell line." (PMID 29426295, 2018). "In line with our previous reports of this trial where patients were classified according to either KRAS exon 2–3/BRAF or extended RAS tissue mutational status, adding cetuximab to chemotherapy and chemoradiotherapy did not significantly improve the outcome of wild-type tumours." (PMID 29362371, 2018). "As well as disease stage, tumor genotype could also be an important determinant of culture success in these conditions: previous studies focus on biopsies and plural effusions from EGFR‐mutant/ALK‐positive tumors, while 7 of our 10 LUAD tumors were driven by mutant KRAS." (PMID 29569246, 2018). "Furthermore, that mutant KRAS-driven MPE is attributed to a CCL2-dependent signalling cascade that is necessary for the sequential translocation of CD11b+Gr1+ cells from the bone marrow to the spleen and the tumour-involved pleural cavity, where, in turn, these cells promote MPE formation." (PMID 28508873, 2017). "Furthermore, targeting KRAS expression, in patients who had KRAS mutant tumours, failed to enhance tumour sensitivity to panitumumab, suggesting that statins could not be used to modulate drug sensitivity in tumours with mutant KRAS." (PMID 28641310, 2017). "Thus it appears that not all KRAS driver substitutions similarly affect fitness in all tumor types." (PMID 26902163, 2016). "However, in that study, while confirming the association between expanding tumor growth, tumor-infiltrating lymphocytes, and loss of MMR protein expression, there was no such association between the presence of KRAS/BRAF mutations and a certain growth pattern or budding intensity in CRC." (PMID 26106602, 2015). "First, because our study lacked data on tumor CIMP (Cpg Island Methylator Phenotype) status and cause of dMMR status, we could not distinguish the correlations of somatic and germline mismatch repair mutations with KRAS and BRAF mutations." (PMID 25929517, 2015). "When tumor and plasma results were considered together, median OS in patients categorized as tissue/plasma KRAS negative/negative, tissue/plasma KRAS discordant, and tissue/plasma KRAS positive/positive were 21.0, 16.9 and 15.4 months, respectively (p = 0.008)." (PMID 25491325, 2014).
tumor (continued). "For this reason, we hypothesized that in the AIO KRK-0104 trial primary tumor location in the left colon might have a favorable prognostic effect in patients with KRAS wild-type tumors, but not in patients with KRAS mutant tumors when receiving cetuximab-based first-line therapy." (PMID 24816724, 2014). "In addition, mutations such as those in KRAS and BRAF that occur early in the development of SBT/LGSC may not be required and/or advantageous for tumor maintenance once additional alterations are acquired." (PMID 25523272, 2014). "In addition, about 40% to 60% of patients with wild-type KRAS tumours do not respond." (PMID 25361007, 2014). "Before detecting the percentage of mutant DNA of tumor tissue, we analyzed the standard curve of the PNA-PCR assay and found the regression line was linear (slope = −3.25; r = 0.977) in the range of 0.02 to 10 ng of KRAS mutant DNA, which means this assay could quantify KRAS mutant DNA." (PMID 23874486, 2013). "Moreover, no relation of KRAS or BRAF mutation and clinical tumor stage was observed." (PMID 24139521, 2013). "Finally, the touchdown PCR and melting conditions of this DPYD HRM assay were suitable for analysis of KRAS, BRAF, and EGFR somatic hotspot mutations in tumor samples (not shown), thus enabling simultaneous analysis of relevant mutations for targeted cancer therapy." (PMID 23335937, 2012). "The downstream PI3K inhibitor, BEZ-235, effectively inhibited tumor cell growth in most of the cell lines tested, except the H1993 and H1650 cells, while the MEK inhibitor PD-325901 was effective in blocking the growth of KRAS mutated cell line H1734 but not H358, A549 and H460." (PMID 22091388, 2011). "When the KRAS mutational status in the primary tumours and the PTEN expression in metastasis were combined, the subgroup of patients with no detectable KRAS mutation and positive to PTEN had a significantly higher response and longer PFS than patients with KRAS mutation and negative to PTEN." (PMID 21139621, 2010). "Furthermore, the identification of oncogenes such as KRAS, MYC, and PIK3CA as being more effective targets than tumor suppressor genes (effect size: 0.87 vs 0.79, P = .03) suggested that oncogene knockout could be a more potent strategy for tumor growth control." (PMID 41517680, 2026). "The knockdown‐KRAS‐SMMC‐7721 xenograft model also showed no significant changes in tumor weight and tumor volume." (PMID 40390765, 2025). "A BCAA-restricted diet (BRD) significantly reduced subcutaneous tumor growth in the KRAS-mutant HCT116 and CT26 models, with no notable effect on KRAS wild-type HT29 and MC38 tumors." (PMID 40437561, 2025). "Our results suggest a prognostic role of IDO-1 protein expression in NSCLC tumor and immune cells independent of EGFR, KRAS AND PD-L1 expression, and should be explored as a predictive biomarker in clinical studies with IDO-1 targeted therapies." (PMID 40475772, 2025). "Tumor number significantly differed between APC; KRAS without DSS vs. APC; KRAS with DSS (P < 0.01), and vs. APC with DSS (P < 0.01); a modest difference was also seen between APC; KRAS with DSS and APC with DSS (P = 0.03)." (PMID 41285904, 2025). "By contrast, in low-immunogenic tumors, while KRAS G12C inhibitors improved antigen presentation and T-cell activation by remodeling the TME, these changes failed to significantly enhance tumor sensitivity to immune checkpoint blockade." (PMID 40303413, 2025). "Finally, to assess whether the observed upregulation of the PCD mediators is induced by mutant KRAS, we treated our acinar explants during our 3-day in vitro ADM assay with the recently developed, KRASG12D-specific inhibitor MRTX1133 that has shown anti-tumor efficacy in several PDAC mouse models." (PMID 39971907, 2025).
tumor (continued). "Using the KRAS mutant GC cell line (AGS) and the KRAS wild-type GC cell line (MKN-45), our data reveal that overexpression of FBXW2 exerts a tumor-suppressing role in both GC cell lines regardless of KRAS mutational status." (PMID 40721413, 2025). "Nonclinical studies demonstrated that FMC-376 results in tumor regression in multiple mouse models including PDX models of NSCLC, PDAC and CR, suggesting its ability to overcome resistance to KRAS G12C (OFF) inhibitors." (PMID 40597785, 2025). "Tumor size also differed significantly between APC; KRAS without DSS and both DSS-treated groups (P < 0.01 and P < 0.01), but not between APC; KRAS with DSS and APC with DSS (P = 0.11)." (PMID 41285904, 2025). "The KRAS p.Lys147Glu was negative in the serrated region, and KRAS p.ALA146THR was negative both in the serrated and the whole‐tumour section." (PMID 40302146, 2025). "Interestingly, a slightly reduced Tm was detected in the group of patients having a nonmutated KRAS at the tumor level compared to their corresponding healthy tissues, suggesting that other CG → AT mutations located at different nucleotide positions of Gly12 and Gly13 could be present." (PMID 39722416, 2024). "The knockdown of KDM6B in PDAC cell lines accelerates tumor growth regardless of KRAS status, despite KDM6B being a downstream target of KRAS." (PMID 38791111, 2024). "All the data suggest a lack of linear relationship between tumor cell percentage and mutant VAFs in BRAF, KRAS, and NRAS in CRC." (PMID 38397405, 2024). "silencing Asf1a in KRAS-mutant LUAD cells using CRISPR-Cas9 increased tumors sensitivity to anti-PD-1 treatment in orthotopic lung cancer models, without affecting tumor cell proliferation." (PMID 38983267, 2024). "The mRNA expression levels of KRAS, ATR, CHEK1 genes in EC tissue samples from both groups with and without recurrence were independent of the depth of tumor invasion into the myometrium." (PMID 38669256, 2024). "Interestingly, using a cohort of 205 samples of CRC patients, including 85 tumour samples with KRAS mutations and 120 tumour samples with KRAS wild type (non-mutated), we detected an association of CBLL1 gene expression with non-mutant KRAS samples, as shown in the boxplot." (PMID 38339195, 2024). "Treatment with P6, a JAK inhibitor, represses tumor proliferation and pSTAT3 phosphorylation in EGFR-mutant cells (11–18, H1650, and H1975) but not in KRAS-mutant cells (H460)." (PMID 37381723, 2023). "In agreement, treatment with anti‐CD3 resulted in massive apoptosis in tumor‐specific CTLs from KRAS mutant, but not wild type, CRC, indicating that tumor‐specific CTLs in KRAS mutant CRC had increased sensitivity to AICD." (PMID 36599679, 2023). "In the C1138 (KRAS G13D) PDX model, the combination of dasatinib and trametinib produced a greater reduction in tumor volume than that in control PDXs but not in PDXs treated with either agent alone." (PMID 36952536, 2023). "We found no concordance of KRAS status between CTC and primary tumours, which is consistent with a previous report." (PMID 37761948, 2023). "With this retrospective study we also assessed the potential correlation between the recently found but not yet implemented marker TSR and molecular tumour markers BRAF, KRAS and MSI." (PMID 37344790, 2023).
tumor (continued). "Interestingly, detection of KRAS tumours’ mutational status is predictive as a negative marker and the patient is unlikely to benefit from EGFR antibody therapy (cetuximab, bevacizumab and panitumumab), so that patients with KRAS wild-type status seem to respond better to anti-EGFR treatment." (PMID 35326950, 2022). "Although the relationship between the perioperative MAF of KRAS and recurrence was not proved, tumor diameter, tumor depth, and stage were correlated with the preoperative MAF of KRAS (p = 0.034, p = 0.002, p = 0.008)." (PMID 35312176, 2022). "The HK1 and HK2 proteins are both highly expressed in KRAS-mutant mouse lung tumors, while the activation of HK2 but not HK1 is inevitable for tumor initiation and progression." (PMID 36532721, 2022). "Tobacco signature was detected in 38–45% of different KRASm and KRAS WT subsets of non-Sq NSCLC but was less frequent in G12R non-Sq NSCLC (22%) and rare in other tumor subtypes." (PMID 36494601, 2022). "Cancer cells in both KRAS-mut and NEK groups conserved members of the MEK family while WT tumor also conserved MAP4K5, which does not have a known role in LUAD." (PMID 36612014, 2022). "Fusions in NTRK genes are more commonly detected in non-Lynch syndrome/MSI-H tumours as well as in wild-type BRAF, KRAS, and NRAS tumours." (PMID 35207616, 2022). "Non-BRAF alterations were detected in four tumor samples consisting of CLIP2:NTRK2, KANK1:NTRK2, RAF1:QKI, and KRAS Q61H." (PMID 36163281, 2022). "Moreover, to assess whether the signature retains its predictive ability in various subgroups, we stratified subgroups by age (age ≤ 60 and age > 60), gender (female and male), tumor location (left-side and right side), TNM stage (stage I-II and stage III-IV), and KRAS mutation (yes and no)." (PMID 35350786, 2022). "A lack of alteration in T cell subsets is supported by previous transcriptomic analysis of stromal cells of KRas-driven mouse tumors, which found no change in the number of CD4+ and CD8+ T cell numbers between tumor and control tissue of the lungs." (PMID 35145525, 2022). "Of note, in 19 cases, sequence variation not previously detected in tumor tissue that emerged under therapy (five NRAS, 14 KRAS)." (PMID 34873826, 2022). "It has been demonstrated that the expression of biomarkers such as KRAS, NRAS, and BRAF, in conjunction with the MSI state of the tumour, serves as a negative predictor for anti-EGFR therapy in mCRC patients." (PMID 36612217, 2022). "Margins over 10 mm were associated with no local progression, especially in patients with KRAS wild-type disease, whereas in RAS mutant tumors, ablation margins larger than 10 mm are mandatory to achieve local cure and sustained local tumor control." (PMID 33672993, 2021). "By using PDOs as a model system for evaluating clinically relevant drug responses, we conclude that KRAS and BRAF, but not MMR status, are dominant factors in determining the intrinsic sensitivity of tumor cells to chemotherapy and targeted therapy." (PMID 34771595, 2021). "In contrast mutant KRas-independent tumors do not require GSK-3β for viability, survival, and tumor growth." (PMID 34955846, 2021). "Subcutaneous injections of HMOsisEC10 KRAS and HMOsisEC10 PIK3CA mutant cells in nude mice did not produce any forms of tumor within two months of monitoring." (PMID 34202354, 2021). "The enthusiasm for FTIs was tempered when it was discovered that in NRAS and KRAS mutant cancers, the MAPK pathway activation and tumor growth were not significantly suppressed with FTIs." (PMID 34830283, 2021).
tumor (continued). "In contrast, in similar experiments performed in the KRAS-dependent A549 cell line, neither MSI2 depletion, erlotinib treatment, nor the combination significantly impaired tumor growth." (PMID 33723247, 2021). "A potential limitation of our study is that MAPK1, KRAS, and NRAS SNPs were analyzed in the blood and not in tumor samples." (PMID 34828284, 2021). "Pure tumor epithelia were isolated from the surrounding tumor microenvironment using LCM, and the presence/absence of the WT copy of the KRAS gene was determined by PCR." (PMID 34573384, 2021). "Although the authors did not formally demonstrate that KRas is a direct translational target of EIF5A, this report provided a mechanistic explanation for the tumor-promoting effect of EIF5A in this type of malignancy." (PMID 33303756, 2020). "Furthermore, as changes in KRAS transcripts were only detected in the pituitary but not in the pancreatic islets or gonads, it is possible that different genes may modify tumour development, in a tissue-specific manner." (PMID 32348957, 2020). "An increase in the CD8/CD4 tumor-infiltrating T-lymphocyte (TIL) ratio was observed in the peptide–lipoplex-treated group and T cells in the spleen were KRAS-G12D-specific and did not respond to WT KRAS peptide." (PMID 33298945, 2020). "The effect of PTPN2 knockdown is no less than that of KRAS knockdown in KRAS-dependent tumor cell lines, suggesting that PTPN2 is required for the cell survival signaling of KRAS." (PMID 33122197, 2020). "Of interest, we identified the top 10 differentially mutated genes between APOBEC-enriched and non-APOBEC-enriched samples, and among these, KRAS, CDHR5, JAK2, and MAP2K4 were previously shown to be closely related to tumor development." (PMID 32670354, 2020). "Mutant KRAS ctDNA was considered to be a better prognostic biomarker for PC, whereas KRAS MAF in tumor tissue was not." (PMID 31850201, 2019). "The non-redundancy of KRAS and NRAS functions, and the high level of tumor heterogeneity observed in CRC, however, suggest wide-ranging clinical and therapeutic implications." (PMID 31816869, 2019). "Particularly illustrative in this regard is case #10 with a primary tumor that was BRAF-positive and KRAS-negative." (PMID 30611220, 2019). "Furthermore, we observe an in vivo reduction in tumor size of gallbladder xenografts in response to Afatinib is paralleled by a reduction in the amounts of phospho‐ERK, in tumors harboring KRAS (G13D) mutation but not in KRAS (G12V) mutation, supporting an essential role of the ErbB pathway." (PMID 30304546, 2019). "ZEB1 also has a tumor suppressive role, independent of its ability to induce EMT, given that ZEB1 is able to induce EMT in both KRAS- and EGFR mutant cell lines." (PMID 31867044, 2019). "In contrast to KRAS MAF in ctDNA, KRAS MAF in tumor tissue was not obviously different in PC patients stratified with either tumor staging or distant metastasis." (PMID 31850201, 2019). "Depletion of RPIA significantly inhibited the tumorigenic activity of KRAS-driven PDAC cells, underscoring the importance of non-oxidative PPP during tumor maintenance." (PMID 31569510, 2019). "Amplification of relevant genes, including AKT1, Kirsten rat sarcoma (KRAS), and proto-oncogene tyrosine-protein kinase Yes (YES1), were detected (data not shown) but were not enriched in the osimertinib-resistant xenograft tumor, osimertinib-3." (PMID 29764505, 2018). "We found that ICIs as salvage therapy, compared to standard chemotherapy with decetaxel, significantly improved OS in patients with KRAS mutant NSCLC, not in those with KRAS wild-type tumor." (PMID 28525386, 2017).